PCSK9 (proprotein convertase subtilisin/kexin type 9)
Description:
Crucial player in the regulation of plasma cholesterol homeostasis. Involved in the disposal of non-acetylated intermediates of BACE1 in the early secretory pathway. Inhibits epithelial Na(+) channel (ENaC)-mediated Na(+) absorption by reducing ENaC surface expression primarily by increasing its proteasomal degradation. Regulates neuronal apoptosis via modulation of LRP8/APOER2 levels and related anti-apoptotic signaling pathways.
Synonyms: NARC-1; PC9; NARC1; FH3; FHCL3; HCHOLA3; LDLCQ1
Tractability: Small molecule: a structure with a bound ligand is known; a high-quality ligand is known; it has a high-quality binding pocket. Antibody: an approved drug acts on it; its Gene Ontology location is reachable by antibodies, with high confidence; UniProt places it where antibodies can reach, with medium confidence; UniProt predicts a signal peptide or a membrane-spanning region. PROTAC: ubiquitination databases record sites on it; a small molecule that binds it is known. Other modalities: a drug acting on it is in phase 2 or 3 trials.
Target class: Enzyme; Serine protease SB clan; Protease; Serine protease; Serine protease S8A subfamily
Gene: Protein-coding gene on chromosome 1 (55,039,445 to 55,064,852, forward strand). Ensembl gene ENSG00000169174.
Subcellular location: Cytoplasm; Secreted; Endosome; Lysosome; Cell surface; Endoplasmic reticulum; Golgi apparatus
Pathways (Reactome):
Metabolism of proteins: Post-translational protein phosphorylation; Regulation of Insulin-like Growth Factor (IGF) transport and uptake by Insulin-like Growth Factor Binding Proteins (IGFBPs)
Transport of small molecules: LDL clearance; VLDLR internalisation and degradation
Gene Ontology:
Molecular function: apolipoprotein receptor binding; endopeptidase activity; low-density lipoprotein particle receptor binding; protein binding; RNA binding; serine-type endopeptidase activity; signaling receptor inhibitor activity; sodium channel inhibitor activity; transporter inhibitor activity; very-low-density lipoprotein particle receptor binding; apolipoprotein binding; low-density lipoprotein particle binding; very-low-density lipoprotein particle binding; serine-type peptidase activity
Biological process: cholesterol homeostasis; low-density lipoprotein particle receptor catabolic process; lysosomal transport; negative regulation of low-density lipoprotein particle clearance; negative regulation of receptor internalization; negative regulation of receptor recycling; negative regulation of receptor-mediated endocytosis involved in cholesterol transport; negative regulation of sodium ion import across plasma membrane; positive regulation of low-density lipoprotein particle receptor catabolic process; positive regulation of neuron apoptotic process; positive regulation of receptor internalization; protein autoprocessing; cellular response to insulin stimulus; cellular response to starvation; kidney development; liver development; neurogenesis; neuron differentiation; regulation of neuron apoptotic process; protein processing; proteolysis
Cellular component: cell surface; cytoplasm; early endosome; endoplasmic reticulum; extracellular region; Golgi apparatus; late endosome; lysosome; PCSK9-AnxA2 complex; perinuclear region of cytoplasm; plasma membrane; endolysosome membrane; endoplasmic reticulum lumen; extrinsic component of external side of plasma membrane; lysosomal membrane; COPII-coated ER to Golgi transport vesicle; endosome
Genetic constraint (gnomAD): Loss-of-function variants: 59 observed, 58.61 expected, observed/expected ratio (o/e) 1.01, 90% interval 0.82 to 1.25. The upper end of that interval is the gene's LOEUF score, 1.25, which puts it in group 5 of 6, group 1 being the genes least tolerant of losing a copy. Missense variants: 870 observed, 918.72 expected, observed/expected ratio (o/e) 0.95, 90% interval 0.89 to 1. Synonymous variants: 387 observed, 391.64 expected, observed/expected ratio (o/e) 0.99, 90% interval 0.91 to 1.08.
Gene-disease validity (ClinGen):
ClinGen rates the evidence that PCSK9 causes each of these diseases.
hypercholesterolemia, autosomal dominant, 3 (autosomal dominant): Definitive. Any familial hypercholesterolemia in which the cause of the disease is a mutation in the PCSK9 gene.
Homologues: Orthologues: chimpanzee PCSK9 (99% identical), macaque PCSK9 (87% identical), pig PCSK9 (81% identical), mouse Pcsk9 (77% identical), rat Pcsk9 (77% identical), rabbit PCSK9 (75% identical), guinea pig PCSK9 (75% identical), tropical clawed frog pcsk9 (58% identical), zebrafish pcsk9 (51% identical), Drosophila melanogaster Fur2 (15% identical), Caenorhabditis elegans kpc-1 (14% identical). Paralogues in human: TPP2 (20% identical), PCSK5 (16% identical), PCSK6 (15% identical), FURIN (15% identical), PCSK4 (15% identical), PCSK7 (15% identical), PCSK1 (14% identical), PCSK2 (13% identical), MBTPS1 (12% identical).
Diseases named in the same sentence as PCSK9 in open-access papers:
PCSK9 is named in the same sentence as 487 diseases in open-access papers, as found by Europe PMC text mining. Sharing a sentence is not in itself a finding about the gene and the disease. The quoted sentences say what the papers report.
Hypercholesterolemia (760 papers, 2006 to 2026). An increased concentration of cholesterol in the blood. "PCSK9 is a gene associated with familial hypercholesterolemia and is involved in other biological processes such as apoptosis, autophagy, and inflammatory responses." (PMID 41828564, 2026). "To address these challenges, we developed a Markov cohort state-transition model to compare the cost-utility of various PCSK9 inhibitor regimens combined with statins for Chinese patients with hypercholesterolemia or at high cardiovascular risk." (PMID 41347175, 2025). "Mice were treated with adeno-associated virus expressing proprotein convertase subtilisin/kexin type 9 and a Western diet to induce hypercholesterolemia and/or partial carotid ligation (PCL) surgery to expose the left common carotid artery (LCA) to d-flow." (PMID 40092444, 2025). "Elevated PCSK9 levels are associated with hypercholesterolemia, particularly in familial cases and PCSK9 inhibitors have recently garnered attention due to their effectiveness in statin-intolerant populations." (PMID 40892857, 2025). "At the current negotiated price, evolocumab 140 mg Q2W is the most cost-effective PCSK9 inhibitor regimen for Chinese patients with hypercholesterolemia or at high cardiovascular risk when added to statin therapy." (PMID 41347175, 2025). "The level of hypercholesterolemia induced by the PCSK9 mutation was comparable to other studies of the PCSK9 minipig." (PMID 40131655, 2025). "Given its pivotal role in lipid metabolism, PCSK9 has emerged as an attractive therapeutic target for managing hypercholesterolemia, liver diseases, and associated cardiovascular conditions." (PMID 40942107, 2025). "The complex regulatory network controlling hepatocyte PCSK9 expression represents a promising target for the therapeutic treatment of hypercholesterolemia and associated cardiovascular diseases." (PMID 40764605, 2025). "A recent review highlights the potential role of proprotein convertase subtilisin/kexin type 9 (PCSK9) inhibitors as an effective alternative for managing hypercholesterolemia in patients with statin-associated IMNM." (PMID 40843675, 2025). "Based on these functions, PCSK9 inhibitors are used to reduce the risk of CVDs, atherosclerosis, and hypercholesterolemia in patients with recent MI and improve patient mortality." (PMID 40357205, 2025). "For example, detecting SNPs in the proprotein convertase subtilisin/kexin type 9 (PCSK9) gene is beneficial to diagnosing hypercholesterolemia and determining the risk of atherosclerosis (AS) and CAD." (PMID 39759113, 2025). "On the other hand, according to the ClinVar database, the PCSK9 SNPs are associated with familial hypercholesterolemia (FH)." (PMID 40864779, 2025). "For primary prevention in very high-risk patients (e.g., familial hypercholesterolemia), targets < 55 mg/dL are justified PCSK9 inhibitors and should be considered earlier in the treatment algorithm for high-risk patients, not just as a last-line therapy." (PMID 40648946, 2025). "PCSK9 is found in chromosome-1 and mutation in that specific gene causes familial hypercholesterolemia." (PMID 39623109, 2025). "Since its discovery, PCSK9 has shifted from being considered a rare cause of hypercholesterolemia to becoming one of the most effective therapeutic targets for cholesterol reduction." (PMID 41226200, 2025). "Gain-of-function mutations in Pcsk9 are linked to familial hypercholesterolemia and the inhibition of PCSK9 is emerging as a novel strategy for the treatment of hypercholesterolemia." (PMID 40606021, 2025). "Male and female C57BL/6N mice were injected with an adeno-associated virus (AAV) encoding gain-of-function in proprotein convertase subtilisin/kexin type 9 (PCSK9) to induce hypercholesterolemia." (PMID 38433753, 2024).
Hypercholesterolemia (continued). "The combination of a relatively large effect size and high frequency makes the PCSK9 rs12117661 variant useful for assessing the long-term effects of using PCSK9 inhibitors to treat hypercholesterolaemia." (PMID 37903942, 2024). "In 2003, rare coding variants in PCSK9, which was then an obscure gene, were reported to cause hypercholesterolemia in humans." (PMID 38226617, 2024). "A 6-month HFD was dominated by hypertriglyceridemia and induced kidney ferroptosis, while PCSK9-GOF caused primarily hypercholesterolemia and ER stress." (PMID 39094771, 2024). "It has been observed that some mutations found within the PCSK9 gene are associated with hypercholesterolemia and with an increased risk of cardiovascular diseases." (PMID 38338741, 2024). "Small-molecule inhibitors targeting PCSK9 provide an effective and safe method for managing hypercholesterolemia and reducing the cardiovascular risk." (PMID 39736777, 2024). "A number of gain-of-function variants in PCSK9, which play a crucial role in maintaining cholesterol homeostasis, result in hypercholesterolemia." (PMID 38796450, 2024). "In conclusion, PCSK9 has emerged as a pivotal therapeutic target with the capacity to redefine the management of hypercholesterolemia and cardiovascular risk." (PMID 38105401, 2024). "The role of Epas1 in atherosclerosis was evaluated by inducible endothelial Epas1 deletion, followed by hypercholesterolemia induction (adeno-associated virus-PCSK9 [proprotein convertase subtilisin/kexin type 9]; high-fat diet)." (PMID 39234692, 2024). "A year later, the association between gain-of-function PCSK9 genetic mutations and hypercholesterolemia was reported, and this discovery opened a new era in lipid-lowering therapies." (PMID 38398257, 2024). "Hypercholesterolemia and atherosclerosis were induced by a tail vein injection of recombinant adeno-associated virus (rAAV) encoding proprotein convertase subtilisin/kexin type 9 (PCSK9) and a high-fat diet for 12 weeks." (PMID 38234375, 2024). "Experimental and clinical research indicates that hypercholesterolemia is influenced not only by PCSK9 “gain‐of‐function” variants but also by the overexpression of the wild‐type protein." (PMID 39150051, 2024). "Mutations in genes related to the LDL receptor (LDL-R), apolipoprotein B (APOB), and proprotein convertase subtilisin/kexin type 9 (PCSK9) are the main molecular mechanisms causing familial hypercholesterolemia." (PMID 39350832, 2024). "This is especially urgent in patients suffering from familial hypercholesterolemia where gain-of-function (GOF) mutations of the PCSK9 gene have been observed." (PMID 38338741, 2024). "Despite not assessing ACS populations, the ARCHITECT study evaluated PCSK9 inhibitor-associated plaque modification on CCTA features of patients with familial hypercholesterolemia." (PMID 39274253, 2024). "Since gain-of-function mutations in Proprotein convertase subtilisin-kexin type 9 (PCSK9) have been identified as contributors to familial hypercholesterolemia, PCSK9 inhibitors have gained attention as novel lipid-lowering treatment." (PMID 38817546, 2024).
Hypercholesterolemia (continued). "We found two variants in APOE, a gene that is associated with coronary artery disease in OMIM, and a variant in PCSK9, a gene that is linked to familial hypercholesterolemia." (PMID 39460944, 2024). "The discovery of functional mutations in PCSK9, which cause familial hypercholesterolemia, and the crystal structure of PCSK9 have identified it as a distinct therapeutic target for cardiovascular disease." (PMID 39404968, 2024). "Patients with type 2 DM on medication and those with the PCSK9 rs151193009 variant showed reduced risk of hypercholesterolemia." (PMID 36980993, 2023). "PCSK9 has been reported as a therapeutic target for patients with dyslipidemia or hypercholesterolemia, and overexpression of PCSK9 is associated with oncogenesis and enhances the malignant phenotypes of CRC with APC/KRAS mutations." (PMID 37215622, 2023). "As a result, the gene PCSK9 is normal but it is expressed in an abnormal form; this is called a gain of function mutation, which leads to the development of FH, and high levels of PCSK9 are linked to hypercholesterolemia." (PMID 38125244, 2023). "In the pathophysiology section, gain-of-function variants in PCSK9 are associated with hypercholesterolemia." (PMID 36980941, 2023). "PCSK9 inhibition has emerged as a potential novel therapeutic approach to treat hypercholesterolemia and associated diseases, such as atherosclerosis." (PMID 36911736, 2023). "Inhibitors of PCSK9 have been approved for the treatment of atherosclerotic cardiovascular diseases associated with hypercholesterolemia, however, a central role on immune tolerance in oncology has recently been investigated." (PMID 36900189, 2023). "PCSK9 rs151193009 reduced hypercholesterolemia risk in Malays, consistent with previous findings on the protectiveness of this variant against high LDL-C and coronary artery disease risk in Asians only." (PMID 36980993, 2023). "PCSK9 is a member of the pro-protein convertase family, and its function in cholesterol metabolism was initially determined in hypercholesterolemia caused by a PCSK9 mutation 44,45." (PMID 37151886, 2023). "Briefly, we induced hypercholesterolemia and atherosclerosis by intraperitoneally injecting mice with an adeno-associated virus that overexpresses proprotein convertase subtilisin/kexin type 9 (PCSK9-AAV) and feeding them a Western diet (WD) for 10 weeks." (PMID 38085578, 2023). "In early 2000, proprotein convertase subtilisin/kexin type 9 (PCSK9), a protein associated with the turn-over of the low-density lipoprotein receptors, was identified as a promising target for hypercholesterolemia treatment." (PMID 38304061, 2023). "Proprotein convertase subtilisin/kexin type 9 (PCSK9), mainly synthesized by hepatocytes and one of the key enzymes in lipid transport, was correlated with an expanded risk for hypercholesterolemia and coronary artery disease." (PMID 37025995, 2023). "Recent PheWAS studies have focused on PCSK9, and all confirm the known association between PCSK9‐inhibitor lipid‐lowering medication and decreased risk of hypercholesterolaemia, hyperlipidaemia and cardiovascular disease." (PMID 37208559, 2023). "Certain missense mutations in the PCSK9 gene can cause dominant hypercholesterolemia in patients by increasing PCSK9 activity." (PMID 38027179, 2023). "Gain-of-function variants in the PCSK9 gene (PCSK9) are associated with hypercholesterolemia, and loss-of-function variants in this gene are associated with hypocholesterolemia and have a more favorable cardiovascular risk profile." (PMID 36980941, 2023).